TLR7 (toll like receptor 7)
Diseases named in the same sentence as TLR7 in open-access papers (continued):
Sharing a sentence is not in itself a finding about the gene and the disease.
infection (continued). "Overall, this analysis implies that RSV infection induces a TLR7-mediated imbalance of Th1/Th2 responses, likely driving an early Th2 skew in the URT followed by a Th1 skew in the LRT later in the infection and pathogenesis process." (PMID 37795093, 2023). "After 48 h of infection, LMH cells infected with FAdV-4 GY (group A) showed significant upregulation of the transcription levels of most immuno-cytokines (IL18, TLR7, IFN-α, and IFN-β excepted), such as OASL, Mx, MDA5, and MAVS." (PMID 37896849, 2023). "Quantitative analysis of protein levels performed by dot blot scanning showed that the expression levels of ACE-2, annexin-V, flotillin-1, TLR-7, LAMP, TNF-α, caspase-1, caspase-8, and others were altered in EVs after infection." (PMID 36979955, 2023). "Of note, despite having an active infection and higher levels of systemic immune activation compared with HIVfree individuals, CD4+ T cells from EC donor expressed low levels of TLR7, insufficient to promote IRF-5 and cell death." (PMID 37227774, 2023). "The addition of agonists to the intracellular TLRs, TLR7, TLR8 and TLR9, prior to infection in PBMCs has been shown to exhibit anti-HIV activity by inducing high levels of the type-1 interferons and interferon-stimulated genes." (PMID 38005883, 2023). "While infection at day 7 increased the CD8+:CD4+ T cell ratio in the lungs of both genotypes, this was significantly lower in TLR7 KO mice." (PMID 37795093, 2023). "To model acute and chronic phases of the disease, we infected wild-type C57BL/6 and toll-like receptor 7 knockout (TLR7 KO) mice with RSV and temporally assessed nasal, airway and lung inflammation for up to 42 days post-infection." (PMID 37795093, 2023). "It has been shown that in a mouse model of infection with L. donovani, IFN-γ+ CD4+ T cells died by apoptosis via TLR7-mediated IRF-5 upregulation of DR5; the authors suggested that this was triggered by tissue disruption." (PMID 35106507, 2022). "Upon pathogen infection, TLR7 interacts with its corresponding ligands, and the intracellular Toll/interleukin-1 receptor homology (TIR) domain of activated TLR7 binds to and interacts with the carboxyl-terminus of MyD88." (PMID 35211622, 2022). "Similar to TLR8, TLR7 mRNA transcript was also increased remarkably at 44.2-fold (P < 0.0001) and 7.8-fold (P < 0.0001) upon J99 and SS1 infection." (PMID 36317079, 2022). "Leukocytes expressed TLR2, TLR3, TLR4, TLR6, and TLR7 can interact with RSV and promote immune responses following infection." (PMID 35308390, 2022). "In particular, SARS-CoV-2 induces toll like receptor-7, TLR7, pathway via NF-κB, inducing type 1 IFN, IFN-γ, and IFN-λ3, starting from 48 h post-infection." (PMID 36582523, 2022). "As expected, TLR3 and TLR7 mRNA levels were increased up to 1.4-fold in GR1−/− and G+/−GR1−/− cell lines after HCoV-OC43 infection compared with infected wild-type cells." (PMID 35897807, 2022). "We first generated Tlr7−/y and WT PTCRA-EGFP reporter mice and monitored pDC motility in the tibial BM of Py infected (36 hr post-infection), or control uninfected live mice using IVM imaging." (PMID 36278864, 2022). "Conversely, TLR7 seems to act mainly via NFκB, inducing type 1 IFN, IFN-γ, and IFN-λ3, starting from the 48 h post-infection." (PMID 34576716, 2021). "During infection to EBV, TLR7/8 (Toll-like receptor 7/8) signaling elevated PD-L1 through MyD88 (myeloid differentiation primary response 88) and IRAK1/4 (interleukin 1 receptor-associated kinase 1/4) signaling." (PMID 34503236, 2021). "Several TLRs have been described as important molecules in the resistance to T. cruzi experimental infection, such as TLR2, TLR4, TLR7, and TLR9." (PMID 34336720, 2021). "We used a model where M-CSF and GM-CSF MФ were primed by infection with LCMV for 1 h prior to stimulation with the TLR7 agonist R848, followed by assessment of TLR7-mediated signalling events and cytokine production." (PMID 33331816, 2021).
infection (continued). "Increased expression levels of TLR3 and/or TLR7, RIG1, and MyD88 genes were detected in response to infection, resulting in the transcriptional upregulation of IFN-λ1 in both ALI-PREC cultures and tracheal epithelia." (PMID 34935443, 2021). "Recently, a new TLR-7 activating agent, named APR002, has been used alone or in combination with Entecavir (ETV) in the woodchuck model of infection." (PMID 34685543, 2021). "Conversely, TLR7 seems to mainly act via NFκB, inducing type 1 IFN, IFN-γ, and IFN-λ3, starting from the 48 h post-infection." (PMID 34576716, 2021). "The role of TLR7 and TLR8 SNPs in SRLVs infection surely requires a comparison of infected and uninfected animals." (PMID 34206971, 2021). "As a critical element in intracellular pathogen recognition, TLR7 gene expression was induced in the kidney and liver as early as 6 h following infection with GSIV and at 48 h post-infection (hpi) in the spleen." (PMID 34675918, 2021). "TLR7 and CCL21 were the only two downregulated genes following H37Rv infection with respect to the uninfected controls." (PMID 34276658, 2021). "The expression of TLR7 and TLR8 in the lungs of BALB/c mice was upregulated during infections with hMPV, reaching peaks by day 5 p.i.." (PMID 33809875, 2021). "In response to TLR7 (imiquimod) stimulation, monocytes had a modest TNF response, which significantly increased at peak infection." (PMID 32566226, 2020). "NDV infection increased the expression of toll like receptor TLR3, TLR7, MDA5, IFN-α, IFN-β, IFN-γ, IL-8, and CXCLi1 in the testes of NDV-infected roosters at 5 days post-infection (dpi)." (PMID 32600413, 2020). "Transcription factors selected as biomarkers for targeting should be predicted for genes such as TLR7, TLR9, RHOA, IRF1, and IL6 since they are activated early in infection." (PMID 32872640, 2020). "To investigate the mRNA of PRRs, IFNs and ISGs in the spleens of H5N6 viruses infected geese, we quantified the mRNA expression of TLR7, TLR3, RIG-I, MDA5, IFN-α, IFN-γ, Mx, and OASL at 12 hours and 3 days post-infection with the two H5N6 viruses." (PMID 32046051, 2020). "We observed an increase in TER119+ cells indicating the activation of extramedullary hematopoiesis, as was described after stimulation with TLR7 and TLR9 ligands as well as after infection with bacteria (Salmonella spp., Ehrlichia spp)." (PMID 32849551, 2020). "Consistent with our gene expression data, stimulation of TLR response with TLR3 and TLR7 agonists, showed almost complete suppression of infection for TLR3 stimulation and partial suppression of infection for TLR7 stimulation in one of the fcMSC donors." (PMID 32941515, 2020). "It has been published that infection of lung epithelial cells with Sendai virus, which is primarily recognized by RIG-I but can also be detected by MDA5 and TLR7, induces the phosphorylation of several mTOR kinase substrates suggesting increased mTOR activity." (PMID 33013932, 2020). "It has been shown, though, that infection of human corneal epithelial cell (HCEC) line by HSV-1, which is a dsDNA virus, can lead to upregulation of TLR7 expression level and proinflammatory cytokine and IFNs production." (PMID 33679688, 2020). "In comparison to the control uninfected group, mRNA expression levels of TLR3, TLR4, TLR7, MyD88, RIG-1 and NF-κB p65 in the control infected group were prominently increased on days 3 and 7 post-infection (all P < 0.01)." (PMID 31551774, 2019). "TLR3, TLR7, and TLR9 are known to be important host factors involved in restricting EV71 infection in diverse infection models in vivo and in vitro." (PMID 31730654, 2019). "CVB3 can induce TLR7 and TLR8 expression after 48 h of infection at a low multiplicity of infection (MOI)." (PMID 31117206, 2019). "During primary infection, EBV downregulates TLR7, TLR8, and TLR9 expression to support viral replication in infected B cells." (PMID 31238570, 2019).
infection (continued). "Among the PRRs expressed in liver tissues, TLR7 activation is essential for the IFN response to both DHAV-1 and DHAV-3 infection." (PMID 31514454, 2019). "Dendritic cells (DC), in particular plasmacytoid DC (pDC), utilize TLR7 to sense VSV, and are major producers of early type-I IFNs following systemic VSV infection." (PMID 30930901, 2019). "Secretion of IL-4 of T lymphocytes from the WT-INF group (CD4: 8.01 ± 1.23%; CD8: 2.1 ± 0.23%) was also higher than TLR7-INF (CD4: 1.43 ± 0.48%; CD8: 0.94 ± 0.14%, P < 0.05) after infection." (PMID 31930147, 2019). "In this study, the mRNA levels of TLR7 and NLRP3 were significantly increased in both infection groups (p < 0.05)." (PMID 31514454, 2019). "BeAn-infected SJL mice express several genes involved in the innate immune responses (Tlr7, Tlr8, Tlr9, Myd88, Isg15, Isg20, Mx1, and IL6) in the spinal cord during the late phase of TMEV-IDD at 165 days post infection." (PMID 30669615, 2019). "In TLR7-mediated neural apoptosis upon EV71-infection, the level of IL-6 was predominantly induced in the cerebral cortex on days 3 and 5 after EV71 infection, and was also specifically modulated by TLR7." (PMID 31730654, 2019). "We next measured the expression of an autophagy gene, Atg5, known to negatively regulate antiviral immune responses in Wt, and TLR7−/− pLN and found that Atg5 expression is reduced at a comparable level in pLN of Wt and TLR7−/− mice after infection." (PMID 30930901, 2019). "Upon infection, the single-stranded RNA (ssRNA) of IAV is detected by pattern recognition receptors (PRRs) such as endosomal toll-like receptor 7 (TLR7) or cytosolic retinoic acid-inducible gene-I (RIG-I)." (PMID 30498445, 2018). "UNC93B1 can facilitate trans-location of TLR (TLR3, TLR7 and TLR9) from the endoplasmic reticulum to the Golgi and mediates the host immune responses to infection with murine cytomegalovirus, as well as several intracellular protozoan parasites." (PMID 29530077, 2018). "Expressions of TLR-7, RIG-I, and MDA5 were also analyzed 6 h post-infection, but were found to be similar for infected and uninfected cells in both cell lines." (PMID 29880757, 2018). "To evaluate the effects of TCMs on anti-virus and development of lung inflammation, we infected wild-type and TLR7 KO C57BL/6 mice with Influenza virus FM1 and applied Oseltamivir and three TCMs 24 h post-infection for 5 days, respectively." (PMID 30151032, 2018). "Here, we show that a highly selective TLR7 agonist, GS-9620, activated HIV from peripheral blood mononuclear cells isolated from HIV-infected individuals with suppressed infection." (PMID 28179531, 2017). "Compared to group Z7, the expression of TLR7 in group Z8R2 was down-regulated between 1 and 12 h after infection, and up-regulated between 24 and 60 h after infection." (PMID 28674528, 2017). "Virulent IOE infection triggers upregulation of several TLRs in liver tissue of infected mice including TLR2, TLR7, and TLR9." (PMID 29049365, 2017). "The TLR7/8 profile is also present in NS1-2 transfected cells, showing a role for NS1-2 in modulating TLR signaling during infection." (PMID 28056773, 2017). "Nevertheless, TLR7 levels and its role in HBV pathogenesis should be looked into other relevant systems like PHH cultures or NTCP-driven in vitro infection of different cell lines." (PMID 28088184, 2017). "The microarray data indicated that TLR expression in chicken B cells exhibited a distinct pattern in response to vvIBDV infection, with decreases in the expression of TLR2, TLR6, and TLR7." (PMID 28086922, 2017). "CSFV Shimen infection results in a significant induction of TLR2, TLR4, and TLR7, but decreased of TLR3." (PMID 28751780, 2017). "As well, infection with viruses such as hepatitis C virus (HCV), human immunodeficiency virus (HIV), and influenza A virus (IAV) also result in upregulation of TLR7 expression in hepatocytes, circulating immune cells, and primary macrophages, respectively." (PMID 28928743, 2017).
infection (continued). "However, in HT-29 cells the levels of IRF7 decreased marginally at 36 hrs, but were shown unchanged at 24 hrs p.i., suggesting that TLR signaling may remain intact and be unaffected, and that TLR7/8 signaling may also function early and decrease only at the late stage of infection in HT-29 cells." (PMID 27007979, 2016). "We performed in vivo and in vitro experiments to show that pattern recognition receptors TLR7 and TLR9 are critical for the IFN-I response and host survival in the mouse model of infection." (PMID 27459510, 2016). "TLR-7 expression increased in ALV-J infected chicks at 1-day post-hatch and suggested that ALV-J was recognized by chicken TLR7 during the initial infection." (PMID 28066434, 2016). "Our results showed that F. hepatica infection significantly downregulated the mRNA expression of TLR1, TLR5, TLR6, TLR7 and TLR10 in PBMC at the acute stage of infection (T2)." (PMID 27661612, 2016). "For instance, IBV 2575 AT infection activated multiple PRR genes, including IFIH1, TLR1LA, TLR2-2, TLR3, TLR4, TLR7, and TLR15." (PMID 27876864, 2016). "The expression of TLR3, TLR7, IL-6, IFN-alpha, IFN-gamma, MHC-I and MHC-II, except for IL-8, were also greater in CEFs than in DEFs in response to infection to both viruses or treatment with poly(I:C)." (PMID 26975566, 2016). "We also observed that up-regulation of hepatic expression of 2OAS-1, RIG-I, TLR3, TLR7, and CXCL10 mRNAs was found as early as 7 days after infection and coincident with serum HCV RNA appearance." (PMID 27788241, 2016). "To better understand the therapeutic mechanism of MJWQH in mice infected with H1N1 virus, we measured the expressions of TLR7, MyD88, TRAF6, p65, p-p65, IκB-α, and p-IKKα/β in lung tissues on days 2 and 4 after infection by using Western blot analysis." (PMID 26089947, 2015). "Infection with encephalomyocarditis virus (EMCV) rapidly reduces platelet count, and this response is attributed to platelet Toll-like receptor 7 (TLR7)." (PMID 25784910, 2015). "HCV infection induced the expression of TNF-α at two hours post-infection and the simultaneous knockdown of both TLR7 and TLR8 (TLR7/8) impaired this induction." (PMID 26023919, 2015). "West Nile virus (WNV) vaccination studies revealed that MyD88 and TLR3 are both required for efficient humoral immune responses, and during a WNV infection Rig-I and MDA5, as well as TLR3 and TLR7 are involved in immune recognition." (PMID 25539593, 2014). "We did not detect any statistically significant increase in expression of TLR3, TLR7, and TLR8 transcripts post-infection, however some trends potentially indicating a viral induction were observed (data not shown)." (PMID 24712747, 2014). "pDC produced type I interferon (IFN-α) via TLR7 activation after Ab-mediated uptake of RSV, or via infection with RSV in purified pDC." (PMID 24303065, 2013). "The levels of TLR3 and TLR7-8 peaked at 5 days after infection, while the levels of TLR4 peaked at 9 days after infection." (PMID 24039959, 2013). "Upon infection of primary bone marrow-derived macrophages (BMDMs), MCMV inhibited nuclear translocation of NF-κB p65 (RelA) after stimulation of TLR7 or TLR9." (PMID 22319449, 2012). "Collectively, to date, the analysis of different mice strains lacking one or multiple TLR pathways demonstrated that TLR2, TLR4, TLR7, and TLR9 play a role in the resistance to infection with T. cruzi, with a degree of redundancy between them." (PMID 22496959, 2012). "When TLR2, TLR7 and TLR8 were silenced, there was a considerable decrease in cytokine secretion in human airway epithelial cells with HRV-6 infection." (PMID 22994237, 2012). "TLR7 mRNA expression was significantly and equally induced by both PR8 and OK/09, about 6 fold over mock at 24 h after infection." (PMID 23185463, 2012). "In vivo VSV-infection induces IFN synthesis in many cell types, using either the cytoplasmic RIG-I pathway or the endosomal TLR7 pathway; however, it is unclear how PKR aids this process." (PMID 22615570, 2012).
infection (continued). "One month following infection with IAV, we found increased levels of IgG1 and decreased amounts of IgG2a in sera of TLR7-/- mice, suggesting that TLR7-/- mice do in fact display a Th2 bias during IAV infection." (PMID 21966467, 2011). "TLR7 and TLR8 are PRRs of interest in the setting of HCV-infection as they can bind ssRNAs and lead to the production of large amounts of the antiviral cytokine interferon-α by dendritic cells." (PMID 22022576, 2011). "A different approach for investigating the roles of TLR7 and TLR8 SNPs in the resolution of HCV-infection would require a comparison of patients who are chronically infected with HCV with individuals that have spontaneously cleared infections." (PMID 22022576, 2011). "We found that the 3d mice are highly susceptible to infection with T. gondii, suggesting the possibility that the combined action of TLR3, TLR7 and TLR9 is critical for host resistance to infection with T. gondii." (PMID 20865117, 2010). "In blood, plasmacytoid DC (pDC) are believed to be primary producers of type I IFN during infection by RNA viruses; in pDC, IFN is induced after nucleic acid recognition by TLR7 and signaling through MyD88 to IRF-7." (PMID 19798431, 2009). "Severity of infection measured by the 8-category ordinal scale (OS), where 1 is not hospitalized and 8 is death, positively correlated with platelet-TLR3 and leukocyte-TLR5, while leukocyte-TLR7 showed an inverse correlation." (PMID 40825056, 2025). "In the early phase of infection, plasmacytoid dendritic cells (pDCs) serve as the predominant IFN-I producers, sensing viral RNA through Toll-like receptor 7/8 (TLR7/8) and activating interferon regulatory factor (IRF)–mediated pathways to secrete large amounts of IFN-α and IFN-β." (PMID 41488678, 2025). "To corroborate TLR7/8 involvement in SARS-CoV-2 sensing, we analyzed the cytokine response of monocytes infected with SARS-CoV-2 and of those treated with enpatoran before infection." (PMID 39963132, 2025). "In littermate mice, without the Yaa locus, non-mucosal MNV infection had an increased ratio of cleaved TLRs to intact TLRs and increased levels of intact TLR7." (PMID 39939342, 2025). "Previous studies have shown that TLR7 is upregulated in various tissues of tongue sole and spotted sea bass upon infection with Gram-negative bacteria, specifically Pseudomonas fluorescence and Vibrio harveyi, respectively." (PMID 40352938, 2025). "Additionally, HEK293T cells coexpressing TLR7 and IFITM3 presented altered infection rates, suggesting a complex relationship in which TLR7 can modulate the host antiviral response, potentially impacting the overall dynamics of hMPV infection." (PMID 40235933, 2025). "Wild type C57Bl/6 and TLR7 knockout (TLR7 KO) mice were infected with the H3N2 IAV strain Hk-X31, and key immune responses in the nasal tissue (URT) and lower airways and lung tissue (LRT) measured after acute infection." (PMID 40442368, 2025). "Our findings also demonstrate that severity of infection and survival correlate with different PRRs between these two blood components; in leukocytes, TLR5 positively correlated and TLR7 negatively correlated with ordinal score, while in platelets, TLR3 was positively correlated." (PMID 40825056, 2025). "This could suggest that enhanced TLR7 signaling due to increased expression of tRF-34-PW5SVP9N15WV2P and tRF-33-PW5SVP9N15WV0E could lead to infection-trigged inflammation in the liver of animals exposed to BVDV and M. bovis." (PMID 39582886, 2024). "TLR7 detects the presence of single-stranded RNA (ssRNA) viruses, including human T-lymphotropic virus 1 (HTLV-1), and triggers antiviral and inflammatory responses that are responsible for infection control." (PMID 39650644, 2024). "Meanwhile, to represent the nuclear translocation of NF-κB p65 with CVS-11 infection via Image Stream analysis, BV-2 cells were pre-treated with or without the TLR7 inhibitor." (PMID 39273091, 2024).